SHBG (sex hormone binding globulin)
Diseases named in the same sentence as SHBG in open-access papers (continued):
Sharing a sentence is not in itself a finding about the gene and the disease.
endometrial cancer (28 papers, 2001 to 2025). Primary or metastatic malignant neoplasm involving the endometrium (mucous membrane that lines the endometrial cavity). "And we discovered that age at menopause, age at menarche, and SHBG levels were causally associated with endometrial cancer even after removing the effects of the other two." (PMID 41427029, 2025). "We found that age at menopause, age at menarche, and SHBG levels were causally associated with endometrial cancer (p < 0.05), with respective SNPs of 107, 194, and 378 and F‐values of 10.88, 19.15, and 24.5." (PMID 41427029, 2025). "We found strong evidence (P < 7.14 × 10−3; 0.05/7 multivariable MR analyses) that approximately 13% of the causal effect of ASAT on increased endometrial cancer risk was mediated by lower SHBG (95% CI = 5% to 20%)." (PMID 40987470, 2025). "Improved insulin sensitivity, SHBG restoration, and reestablishment of hormonal balance collectively reduce endometrial cancer risk." (PMID 41301707, 2025). "This positions SHBG within a key endocrine‐metabolic cross‐talk that directly influences endometrial cancer risk." (PMID 41427029, 2025). "Genetic alterations of the SHBG gene are also correlated with a lower risk of ovarian cancer, endometrial cancer, or esophageal squamous cell carcinoma, whereas some alleles increase the risk of non-small lung cancer—UGT2B7." (PMID 40427034, 2025). "Age at menarche and SHBG levels are negatively associated with the incidence of endometrial cancer, while age at menopause is positively associated with it." (PMID 41427029, 2025). "In mediation analyses, we found evidence that fasting insulin, bioavailable testosterone concentrations and SHBG partially mediated the effect of BMI on overall endometrial cancer risk." (PMID 35436960, 2022). "Our systematic evaluation of 14 previously reported candidate mediators of the effect of BMI on endometrial cancer risk identifies fasting insulin, bioavailable testosterone and SHBG as plausible mediators of this relationship." (PMID 35436960, 2022). "Several epidemiological studies have consistently shown that high levels of SHBG in the blood are associated with a reduced risk of endometrial cancer in postmenopausal women." (PMID 35615721, 2022). "The inverse association between SHBG and endometrial cancer has been documented in previous studies and supported by this study." (PMID 35218343, 2022). "We found strong evidence for a mediating role of fasting insulin, bioavailable testosterone and SHBG in the effect of BMI on endometrial cancer risk." (PMID 35436960, 2022). "Increase in androgens and estrogens, and decrease in SHBG and progesterone causes endometrial cancer." (PMID 29201145, 2017). "Accordingly, there is some evidence that genetic variants that have been shown to increase SHBG levels are also associated with a lower risk of endometrial cancer." (PMID 26134033, 2015). "In support of this etiology, decreased plasma sex hormone binding globulin (SHBG) levels and elevated estrogen levels are associated with increased endometrial cancer risk." (PMID 22254087, 2011). "In line with the well-established estrogen-mediated etiology of endometrial cancer, higher intake of caffeinated coffee or caffeine has been associated with increased blood levels of sex hormone binding globulin in postmenopausal women." (PMID 22254087, 2011). "We assessed the association of postmenopausal serum levels of oestrogens and sex hormone-binding globulin (SHBG) with endometrial cancer risk in a case–control study nested within the NYU Women's Health Study cohort." (PMID 11286480, 2001). "Our study showed that age at menarche (p = 1.21e − 05; OR : 0.6852; 95% CI: 0.5784–0.8116), age at menopause (p = 0.00098; OR : 1.242; 95% CI: 1.0919–1.4127), and SHBG levels (p = 7.4e − 07; OR : 0.5914; 95% CI: 0.4804–0.7281) have independent causal relationships with endometrial cancer." (PMID 41427029, 2025).
endometrial cancer (continued). "We found the inverse effect of SHBG on endometrial cancer risk was largely attenuated upon adjustment for bioavailable testosterone, suggesting a protective effect of SHBG may be driven via binding of biologically active fractions of circulating testosterone." (PMID 35436960, 2022). "In addition, lower blood levels of SHBG are also associated with increased endometrial cancer risk, presumably because SHBG binds to estradiol, thereby reducing the levels of bio-available estrogen." (PMID 22254087, 2011). "Physical activity is hypothesised to decrease endometrial cancer risk because it reduces serum levels of estradiol and increases levels of sex hormone binding globulin (SHBG), the binding protein for estradiol." (PMID 20877336, 2010). "High levels of SHBG could reduce the risk of endometrial cancer and PCOS." (PMID 38075074, 2023). "Additionally, it was inversely associated with endometrial cancer among SHBG gene Asp/Asp carriers." (PMID 26114387, 2015). "Previous studies have suggested an inverse correlation between SHBG and endometrial cancer, which is consistent with the findings of this study." (PMID 41427029, 2025). "We discovered that there is an independent causal relationship between age at menopause, age at menarche, and sex hormone–binding globulin (SHBG) levels and endometrial cancer." (PMID 41427029, 2025). "sex hormone-binding globulin (SHBG) is a protective factor against endometrial cancer (OR = 0.823, P < 0.001) and PCOS (OR = 0.715, P = 0.031)." (PMID 38075074, 2023). "The effect of SHBG on overall endometrial cancer fully attenuated when bioavailable testosterone (a presumed downstream mediator of SHBG) was included in the model (OR per increase in INT nmol/L SHBG 1.08, 95% CI 0.86 to 1.36, P = 5.00 × 10−1)." (PMID 35436960, 2022). "C-peptide, insulin, C-reactive protein, leptin, IL-1Ralpha, and IL-6 decreased significantly, while SHBG, IGFBP1, and adiponectin increased significantly in weight-loss interventions in endometrial cancer." (PMID 31440472, 2019). "Insulin indirectly induces the pathogenesis of endometrial cancer by inhibiting the synthesis of sex hormone‐binding globulin (SHBG), which normally binds to androgens and estrogens." (PMID 29533014, 2018). "Alterations in SHBG (sex hormone-binding globulin), progesterone and estrogen due to excess weight induce endometrial cancer." (PMID 29201145, 2017). "Physical activity may protect against endometrial cancer by reducing estradiol and increasing sex hormone binding globulin levels, partly via promoting a healthy body weight." (PMID 41261199, 2025). "Robust and probable evidence was also found for the positive association of genetically predicted testosterone concentrations with risk of breast and endometrial cancer, and the negative association of SHBG with endometrial cancer." (PMID 35105367, 2022). "When combining pairs of mediators together into a single model, we found evidence that an effect of fasting insulin on endometrial cancer was partially mediated by SHBG levels and that an effect of SHBG on endometrial cancer was largely mediated by bioavailable testosterone levels." (PMID 35436960, 2022). "Of the PheWAS traits with available GWAS data, 13 demonstrated evidence of a significant genetic correlation with endometrial cancer, including SHBG, testosterone, the impedance of arm (related to body mass index) and apolipoprotein A (a key constituent of HDL)." (PMID 34675350, 2021). "Negative correlation between SHBG concentrations and the endometrial cancer (EC) risk was found." (PMID 40427034, 2025). "Subsequent analyses highlighted a potentially mediating role of SHBG in the effect of ASAT on endometrial cancer, although we note the potential for weak instrument bias in this analysis." (PMID 40987470, 2025).
endometrial cancer (continued). "High levels of TT and BioT could increase the risks of both endometrioid endometrial cancer and non-endometrioid endometrial cancer, while SHBG was considered to be a protective factor for endometrial cancer." (PMID 38075074, 2023). "Thirteen robust associations were observed in the steroids category, pertaining to the positive association of different measures of testosterone with breast (total, ER+) and endometrial cancer, and to the negative association of sex-hormone-binding globulin (SHBG) and endometrial cancer." (PMID 35105367, 2022).
hypothyroidism (28 papers, 2013 to 2025). Abnormally low levels of thyroid hormone. "In conclusion, our study revealed a significant association between hypothyroidism and SHBG levels above the 99th percentile, which is an indicator of estrogen-containing OCP use." (PMID 40135042, 2025). "This study is the first to explore the associations among OCP use, SHBG levels, and hypothyroidism within the Qatari population." (PMID 40135042, 2025). "In women, higher T PGS was additionally associated with lower hypothyroidism risk (HR = 0.97, p = 6.5e-05), persisting SHBG adjustment (HR = 0.97, p = 8.6e-05)." (PMID 36653534, 2023). "It is a matter of fact that both hypothyroidism and hyperthyroidism are associated with changes in concentrations of SHBG, testosterone, and E2." (PMID 36735200, 2023). "While hyperthyroidism is associated with elevated sex-hormone-binding globulin (SHBG) levels, human studies have reported that hypothyroidism leads to a reduction in levels of SHBG and total serum testosterone." (PMID 35054403, 2021). "In conclusion, increases in SHBG levels were associated with hypothyroidism in this model." (PMID 40135042, 2025). "Furthermore, higher SHBG levels are associated with higher odds of hypothyroidism among OCP users, and the odds of hypothyroidism vary across different ethnicities." (PMID 40135042, 2025). "In this cross-sectional study of 1001 female participants with a current or previous history of estrogen-containing OCP use, we found a 10-fold increase in the odds of hypothyroidism in participants with SHBG levels above the 99th percentile." (PMID 40135042, 2025). "Such conduct leads to a significant decrease in SHBG levels through the mechanism of induced hypothyroidism." (PMID 40427034, 2025). "Altered thyroid function, leading towards hypothyroidism, induces implications on SHBG concentrations." (PMID 40427034, 2025). "Our findings also indicate that the odds of hypothyroidism increase with each successive increase in the SHBG quartile, with poor evidence against the null." (PMID 40135042, 2025). "The incremental increases in the odds of hypothyroidism with SHBG quartiles and increased SHBG percentile cutoffs suggest a positive association between these variables." (PMID 40135042, 2025). "Hypothyroidism in PCOS is associated with increased body weight, increased sex hormone-binding globulin (SHBG), androstenedione to testosterone conversion increase, and aromatization to estradiol." (PMID 37118753, 2023). "We have demonstrated that FT4, FT3, rT3, cholesterol, and SHBG show significantly different values on LT4 treatment compared with LT3 treatment in women with hypothyroidism and residual symptoms despite normal TSH levels." (PMID 35572853, 2022). "Hypothyroidism also lowers the synthesis of sex hormone-binding globulin (SHBG) and affects the peripheral consumption of estrogen." (PMID 35291534, 2022). "In this setting, FGF21 serum level positively correlated with rising serum triglycerides, and negatively with SHBG, which was typically reduced in hypothyroidism." (PMID 35909532, 2022). "In other endocrine diseases such as hypothyroidism, decreased levels of circulating SHBG have been observed, whereas hyperthyroidism leads to increased plasma SHBG levels." (PMID 34335746, 2021). "In PCOS, the levels of circulating SHBG are decreased compared with control women in a 25%–45% as compared with normal levels, whereas in hypothyroidism, the relation is almost the same." (PMID 34335746, 2021). "In hypothyroidism, plasma binding activity of SHBG is decreased, which results in decreased plasma concentrations of both total testosterone and E2, but their unbound fractions are increased." (PMID 28723963, 2017). "Serum SHBG, an indicator of hypothyroidism in the liver, was significantly correlated with free T4 (FT4) concentrations in treated and untreated adult patients (r = 0.583, P = .002) and also after correction for body mass index (BMI) (corrected P = .003)." (PMID 26840047, 2016).
hypothyroidism (continued). "However, at the 95th percentile of SHBG values, there was 46% higher odds of hypothyroidism (OR 1.46, 95% CI 0.33–6.54) and an over tenfold increase at the 99th percentile (OR 10.07, 95% CI 1.94–52.45, p=0.006)." (PMID 40135042, 2025). "As in the case of hypothyroidism, hyperthyroidism leads to increased concentration of SHBG." (PMID 40427034, 2025). "What is more, this phenomenon marks its influence on lower SHBG concentrations followed by higher free and total testosterone levels in postmenopausal women with HT diagnosis, thus occurring autoimmunity in patients with hypothyroidism." (PMID 40427034, 2025). "Patients with confounding factors that may induce a decrease in SHBG, such as hypothyroidism, were excluded from our study." (PMID 37568345, 2023). "However, interestingly, a reduction of SHBG is also seen in patients with myxedma, a condition which is a complication of hypothyroidism and is also almost exclusive to women." (PMID 25133674, 2014). "Hypothyroidism may result in a decrease in the sex hormone binding globulin (SHBG) levels and a decrease in total serum testosterone levels, as well as a decrease in the LH and the follicle stimulating hormone (FSH) levels." (PMID 24312078, 2013). "Since low SHBG levels are associated with an increased risk of cardiovascular events, our findings together with the observed reduction in LDL cholesterol on LT3 treatment might improve cardiovascular status in patients with hypothyroidism." (PMID 35572853, 2022). "A reduction in the metabolic clearance rates of androstenedione and estrone, along with a decrease in the plasma binding activity of sex hormone-binding globulin (SHBG), are some of the effects of hypothyroidism on female reproductive hormones." (PMID 40237055, 2025). "Thyroid abnormalities—hypothyroidism, hyperthyroidism, TNs, and THR syndrome are proven to be affected by the SHBG." (PMID 40427034, 2025). "In radioiodine-induced hypothyroidism, the rising serum FGF21 concentration correlated positively with rising serum triglycerides and negatively with falling SHBG, reflecting increased hepatic lipogenesis." (PMID 35909532, 2022). "In hypothyroidism, levothyroxine substitution leads to higher SHBG levels, normalization of total cholesterol and triglycerides, and an increase in HDL concentration." (PMID 40427034, 2025). "Multinomial logistic regression revealed no increased odds of hypothyroidism at the 90th percentile cutoff for SHBG levels (OR 1.00, 95% CI 0.29–3.50)." (PMID 40135042, 2025). "In addition, we observed higher levels of MMP, SHBG in women diagnosed with a thyroid disorder (hypothyroidism or thyroid cyst) compared to women without thyroid disorder." (PMID 35327785, 2022). "Interestingly, studies are not unambiguous in the case of SHBG and hypothyroidism per se." (PMID 40427034, 2025). "Among the endocrine features, patients with primary overt hypothyroidism may have mild increase in total testosterone (T) and free testosterone (fT) total and free estradiol, prolactin (PRL) and luteinizing hormone (LH), and decreased sex hormone binding globulin (SHBG) levels." (PMID 28868249, 2017).
hyperthyroidism (25 papers, 2011 to 2025). Overactivity of the thyroid gland resulting in overproduction of thyroid hormone and increased metabolic rate. "What is more, ovarian abnormalities associated with SHBG alterations can normalize in women with clinical hyperthyroidism after the usage of thiamazole." (PMID 40427034, 2025). "Physiological research indicated that hypo- and hyperthyroidism were linked to sex hormone-binding globulin, sex hormone levels, ovarian reserve, and even sexual function." (PMID 39429737, 2024). "T4 has previously been shown to be positively associated with SHBG levels in men with hyperthyroidism and inversely associated with SHBG levels in men who are hypothyroid." (PMID 29995902, 2018). "Imbalance between testosterone and estrogen is caused by some kinds of sex hormone-binding globulin, which may be present in hyperthyroidism, chronic liver diseases and the use of medications, such as spironolactone." (PMID 22047550, 2011). "SHBG levels are increased in hyperthyroidism in proportion to the levels of thyroxine (T4) and triiodothyronine (T3) in children as in adults, and values normalize when hyperthyroxinemia is treated." (PMID 40863113, 2025). "Women with clinical hyperthyroidism (mostly GD, toxic nodular goiter, HT) possessed higher SHBG concentrations in comparison to the healthy age-matched control group." (PMID 40427034, 2025). "In GD, women with hyperthyroidism are found to have higher SHBG concentrations, despite the anti-thyroid treatment." (PMID 40427034, 2025). "For example, a study examining the relationship between hyperthyroidism and SHBG levels reported that 69% of the 82 patients sampled had elevated SHBG levels." (PMID 40135042, 2025). "Sex hormone-binding globulin (SHBG) was elevated at 111 nmol/L (reference range 13–89), suggesting hyperthyroidism in addition to liver disease." (PMID 40259920, 2025). "Hyperthyroidism, particularly in conditions like Graves’ disease, increases hepatic SHBG production, which reduces free testosterone levels while elevating the estrogen-to-testosterone ratio, a key driver of gynecomastia." (PMID 39797240, 2024). "For instance, THs have been shown to influence concentrations of SHBG, as evidenced by elevated testosterone and SHBG levels in males with hyperthyroidism." (PMID 39104813, 2024). "Hyperthyroidism is characterized by increased total thyroxine (T4) levels which lead to an increase in sex hormone binding globulin (SHBG) in circulation and a decrease in the level of testosterone." (PMID 37886048, 2023). "Increased levels of SHBG in humans are a well-known feature of hyperthyroidism, which results in elevated levels of serum testosterone." (PMID 35054403, 2021). "Compared to healthy controls, individuals with hyperthyroidism have been shown to possess greater levels of SHBG and LH, but lower free testosterone levels." (PMID 35054403, 2021). "An effect of SHBG on gonadotropin and sex steroid secretion is implied from observations in men with hyperthyroidism who typically have high serum levels SHBG as well as LH and testosterone." (PMID 33014416, 2020). "Women with hyperthyroidism have estrogen levels 2- to 3-fold higher compared to euthyroid women due to SHBG changes and decreased clearance of estradiol." (PMID 23956749, 2013). "Weight loss, fasting, hyperthyroidism, or thyroid hormone treatment, growth hormone pulsatility promote hepatocyte nuclear factor 4 alpha (HNF-4α) activity, resulting in increased hepatic synthesis of the major SHBG fraction." (PMID 40427034, 2025). "Relations between hyperthyroidism, SHBG, and ultrasonographic ovarian image have been found." (PMID 40427034, 2025). "Other substances such as sex hormone binding globulin (SHBG), cholesterol, angiotensin-converting enzyme, soluble interleukin-2 receptor, osteocalcin, carboxy-terminal cross-linked telopeptide of type I collagen (ICTP) can also be used as clinical indicators for the evaluation of hyperthyroidism." (PMID 33329389, 2020).